SNORD81 (Small nucleolar RNA SNORD81 )
Synonyms: LOC124900199
Gene: Small nucleolar RNA gene on chromosome 5 (18,236,123 to 18,236,196, forward strand). Ensembl gene ENSG00000212278.
Gene Ontology:
Biological process: RNA processing
Cellular component: nucleolus
Homologues: Orthologues: macaque SNORD81 (93% identical), rabbit SNORD81 (80% identical), rat Snord81 (80% identical), pig SNORD81 (78% identical), mouse Gm25789 (77% identical), mouse Gm25802 (76% identical), guinea pig SNORD81 (68% identical), guinea pig SNORD81 (61% identical). Paralogues in human: SNORD81 (78% identical), SNORD81 (73% identical).